BDNF (brain derived neurotrophic factor)
Diseases named in the same sentence as BDNF in open-access papers (continued):
Sharing a sentence is not in itself a finding about the gene and the disease.
depression (continued). "Reduced NGF and BDNF signaling in the adult brain may be involved in the pathophysiology of psychiatric disorders, such as depression, and a role for NGF has been proposed in the etiopathogenesis of schizophrenia." (PMID 22474604, 2012). "Our in vivo and in vitro findings indicate that the BDNF response after antidepressant treatment is more complex than predicted by the neurotrophin hypothesis of depression." (PMID 22581450, 2012). "This study was not designed to investigate the association of BDNF levels and the prevalence of depressive disorders in specific stages of COPD." (PMID 23245944, 2012). "Another reason that discourages the view of decreased hippocampal neurogenesis or BDNF levels as etiological factors of depression is that the blockade of hippocampal neurogenesis or conditional deleted expression of BDNF in male mice do not induce a depressive-like behaviour." (PMID 22654714, 2011). "Our results further contribute to the hypothesized association between HPA axis dysregulation and reduced neuroplasticity in depression and are consistent with the assumption that BDNF is a stress-responsive intercellular messenger modifying HPA axis activity." (PMID 22194899, 2011). "In conclusion, data reveals that a wide range of neurotrophic factors besides BDNF may be potential candidates for the development of better and with lesser side-effects treatments for depression." (PMID 22654714, 2011). "Additionally, both BDNF- and serotonin-mediated signalling regulate the development and plasticity of neural circuits involved in mood disorders such as depression and anxiety." (PMID 22654714, 2011). "BDNF mRNA levels in the hippocampus have also been shown to be significantly increased with physical exercise and electroconvulsive therapy, which is sometimes used as a treatment for depression." (PMID 22654716, 2011). "Several studies have led to the formulation of the Neurotrophic Hypothesis of Depression, which postulates that low levels of brain-derived neurotrophic factor (BDNF) lead to a depression condition." (PMID 22654714, 2011). "However, there is an evident overlap in the BDNF levels between these patients with depression and healthy controls." (PMID 21912609, 2011). "There is also large number of studies suggesting a major role of BDNF in depression." (PMID 22194899, 2011). "In fact, since a number of studies showed decreased blood BDNF levels in patients with major depression, it is possible that blood BDNF levels could serve as a potential biomarker for major depression." (PMID 21912609, 2011). "Most association studies of BDNF polymorphism and depression related traits have yielded negative results." (PMID 22194899, 2011). "The role of BDNF in depression was recently reviewed by several investigators." (PMID 21306618, 2011). "This decrease in BDNF expression results in decreased hippocampal neurogenesis, and may consequently contribute to the hippocampal atrophy observed in depression." (PMID 21151517, 2011). "Initially, it was suggested that low levels of BDNF lead to a depression state." (PMID 22654714, 2011). "Some studies also suggest a gender specificity in what concerns BDNF levels during depression." (PMID 22654714, 2011). "It is crucial then to not overlook the genetic impact of carrying serotonin transporter (5-HTT) gene polymorphisms on development of depression, nor the possible interrelation with a BDNF polymorphism." (PMID 22654714, 2011). "To investigate whether these TrkB agonists mimic BDNF in suppressing depression-like symptoms, we conducted a forced swim test after subchronic treatment of the mice for 5 days with various drugs." (PMID 20644624, 2010). "Thus, BDNF and its receptor TrkB, have become promising targets of novel-type anti-depression therapies." (PMID 20219105, 2010).
depression (continued). "The absence of an association between A/D and variation in serotonergic genes and BDNF is in agreement with genome-wide association (GWA) analyses of major depression whose results did not suggest an association with previously investigated genes." (PMID 20633049, 2010). "Results from clinical and basic studies have demonstrated that stress and depression decrease BDNF expression and neurogenesis, leading to the neurotrophic hypothesis of depression." (PMID 20190960, 2009). "The results from this study, together with the results from our study using an animal model of childhood depression, might indicate that BDNF has a key role in childhood depression." (PMID 21152205, 2009). "However, it is noteworthy to mention, that the evidence for the involvement of BDNF in the pathophysiology of depression is currently inconsistent." (PMID 21152205, 2009). "Several lines of evidence suggest that BDNF might be an important agent of therapeutic recovery from depression, and it might also provide protection against stress-induced neuronal damage." (PMID 21152205, 2009). "The results imply that DHEA(S) and BDNF may be involved in the pathophysiology and pharmacotherapy of childhood depression." (PMID 21152205, 2009). "Down-regulation of the (Trk-B)-BDNF pathway is observed in major depressive disorder." (PMID 19506722, 2008). "The results contradict with the common BDNF hypothesis of depression that predicts decreased levels of BDNF mRNA in depression-related brain areas." (PMID 18177844, 2008). "One explanation is that S100B may be a prerequisite for neuroplastic changes that is required to improve depression, whereas BDNF may reflect the current state of recovery." (PMID 20046365, 2008). "In the contrary, intraventral tegmental area infusion of BDNF induced depression like states." (PMID 19506722, 2008). "Serotonin (5-HT) system has a significant role in anxiety- and depression-related states and may be influenced by brain-derived neurotrophic factor (BDNF)." (PMID 18177844, 2008). "For example, the possibility has to be considered that the change in BDNF levels in rodent models of anxiety and depression might indicate an attempt towards neurochemical adaptation that remains unsuccessful in behavioural regulation." (PMID 18177844, 2008). "Decreases of BDNF levels are accompanied by and are believed to lead to several pathologies, including neuropsychiatric disorders like anxiety-related behaviours, depression, bipolar disorder, schizophrenia and neurodegenerative disorders like Huntington's, Parkinson's and Alzheimer's diseases." (PMID 18177844, 2008). "Also, differential regulation of BDNF mRNAs can take place for example in depression, stress, exercise, and learning." (PMID 17149751, 2007). "Secreted pro-BDNF activates a heteromeric receptor complex of p75 and sortilin to initiate cell death and binds to p75 in hippocampal neurons to enhance long-term depression." (PMID 17149751, 2007). "It has also been shown that histone modifications at specific BDNF promoters are involved in chromatin remodeling during electroconvulsive seizures and cocaine-induced plasticity in rat and in a mouse model of depression and antidepressant treatment." (PMID 17149751, 2007). "Further, the results of a study are consistent with the hypothesis that decreased expression of BDNF and possibly other growth factors contributes to depression and that upregulation of BDNF plays a role in the actions of antidepressant treatment." (PMID 16995950, 2006). "Furthermore, in patients with major depression, serum BDNF levels were decreased, while hippocampal BDNF immunoreactivity was increased in post-mortem tissues from subjects treated with anti-depressants." (PMID 15876359, 2005). "The handling-induced changes in BDNF and 5-HT1A receptors could underlie the previously documented effect of handling in preventing "depression"." (PMID 15876359, 2005).
depression (continued). "This aligns with findings from genetic studies of depression and anxiety, which have suggested that BPAD shares common genetic risk factors with these disorders, particularly those related to the serotonin transporter gene (SERT) and brain-derived neurotrophic factor (BDNF)." (PMID 41481605, 2026). "Thus, KREO prevents depression-like behavior by enhancing monoaminergic neurotransmission and attenuating hypothalamic-pituitary-adrenal (HPA) axis hyperactivity, with these effects associated with activation of the BDNF signaling pathway." (PMID 42255682, 2026). "The objective of this article was to investigate the levels of BDNF, cognitive function, and SQ in elderly people with MDD and SS, revealing the potential role of these factors in depression management and intervention opportunities." (PMID 40821647, 2025). "Additionally, the excessive activation of the hypothalamic–pituitary–adrenal axis leads to elevated levels of glucocorticoids, as well as reduced secretion of the brain-derived neurotrophic factor (BDNF), which also play important roles in the onset of depression." (PMID 39796425, 2025). "Moreover, a reduction in the expression of neurotrophic factors such as brain-derived neurotrophic factor (BDNF) and vascular endothelial growth factor (VEGF), along with decreased receptor activity, represents a significant alteration associated with depression." (PMID 40365616, 2025). "Additionally, stratifying patients by depression subtype or inflammatory profile may help clarify the role of the tPA/BDNF pathway in specific subpopulations." (PMID 40725146, 2025). "We used lipopolysaccharide (LPS) to establish the depression model and assessed depressive‐like behaviors using various behavioral tests, neuroplasticity, tryptophan pathway metabolites, and brain‐derived neurotrophic factor (BDNF) in serum and prefrontal cortex (PFC)." (PMID 40672547, 2025). "Moreover, exploring the molecular mechanisms underlying their antidepressant effects, such as modulation of BDNF, neuroplasticity, and inflammatory pathways may provide important insights into novel therapeutic targets for treatment-resistant depression." (PMID 41304909, 2025). "Chronic stress has been shown to reduce BDNF levels, which reduces GR phosphorylation and plasticity, and enhancing GR phosphorylation could represent a potential therapeutic approach for psychiatric disorders like depression." (PMID 40362450, 2025). "The independence of BDNF levels from depression and anxiety symptoms that occurred across three different levels of mood severity suggested that chronic cocaine consumption might intricate a relationship between BDNF and mood regulation in CUD." (PMID 40943216, 2025). "Moreover, the BDNF gene, essential for neuronal plasticity and development, has been extensively linked to psychiatric disorders in the adult population, especially PTSD and depression." (PMID 41300812, 2025). "Additionally, AGM promotes neuroplasticity by activating melatonin receptors and upregulating brain-derived neurotrophic factor (BDNF) expression, demonstrating notable therapeutic effects in patients with depression linked to sleep disorders and neurofunctional impairments." (PMID 40977685, 2025). "Furthermore, BDNF is considered a potential biomarker for depression." (PMID 40491453, 2025). "As one of the most commonly examined biomarkers for diagnosis and treatment response in MDD, peripheral BDNF has also been examined in perinatal depression." (PMID 41440970, 2025). "Moreover, they align with previous studies indicating that sex differences in BDNF/TrkB signaling could contribute to differential vulnerability to stress‐related psychiatric disorders, such as depression." (PMID 40762328, 2025).
depression (continued). "Similarly, Xu and Liang (2021) showed that Vitamin D3/VDR signaling mitigates post-stroke depression by upregulating hippocampal BDNF, and Numakawa and Kajihara (2025) emphasized that impaired BDNF–TrkB signaling is a hallmark of depression, schizophrenia, and neurodegeneration." (PMID 41226472, 2025). "Moreover, inflammation may exacerbate the pathological process of depression by affecting brain-derived neurotrophic factor (BDNF) levels, which in turn hinders neuronal growth and survival." (PMID 40358153, 2025). "A substantial body of evidence indicates that BDNF levels are altered in patients with MDD, particularly showing reduced blood BDNF levels in acute MDD patients and in animal models of depression." (PMID 39819542, 2025). "Therefore, gender‐specific approaches to increasing BDNF levels may be necessary to effectively treat depression in females." (PMID 41194467, 2025). "Indeed, the stress-sensitive and depression-prone RLA rats show lower BDNF and trkB protein content in the hippocampus compared to RHA rats, consistent with the greater susceptibility of RLA rats to stress-related depression-like symptoms (and references therein)." (PMID 40867109, 2025). "Therefore, BDNF is not only crucial for understanding the pathophysiology of depression but may also be a key target for the development of new therapeutic strategies." (PMID 40863989, 2025). "Given these interconnected mechanisms, potential treatments for depression may include strategies to upregulate BDNF, block inflammatory cytokine signaling, enhance antioxidant defenses, restore neurotransmitter balance and reverse the deficits, thereby alleviating depressive symptoms." (PMID 40832603, 2025). "Additionally, BDNF interacts with neurotransmitter systems such as serotonin, dopamine, and glutamate, enhancing neurotransmitter availability and receptor sensitivity, thereby improving mood and reducing symptoms of depression and anxiety." (PMID 40002745, 2025). "However, the molecular pathways between Nrf2 and BDNF in depression are poorly known." (PMID 40149774, 2025). "Depression may influence cognitive function through mechanisms including increased cortisol levels, inflammatory processes, and reduced brain-derived neurotrophic factor (BDNF)." (PMID 40630402, 2025). "Reduced BDNF levels may play a role in inflammation, aging, neurodegenerative disorders, and psychiatric conditions such as bipolar disorder and major depressive disorder, suggesting that systemic or localized neurophysiological factors might influence these results." (PMID 41583708, 2025). "Similarly, individuals with depression had lower serum BDNF levels compared to healthy volunteers." (PMID 40002745, 2025). "For RDCS<0h, the increased depression vulnerability may involve inflammatory activation impairing serotonin synthesis through the kynurenine pathway, coupled with reduced Brain-Derived Neurotrophic Factor (BDNF) l levels that compromise neural plasticity and emotional regulation." (PMID 40687274, 2025). "Furthermore, poor sleep quality may impair positive emotional response, mood regulation, short-term memory, and attention, while also reducing levels of brain-derived neurotrophic factor—thereby contributing to the onset of depression." (PMID 41409334, 2025). "Although the concentrations of these two indicators were higher than those in patients with depression in other age groups and exhibited a significant increase after 4 weeks of intervention, they still fell considerably below the normal reference range for BDNF and 5-HT." (PMID 41477617, 2025). "Additionally, taVNS's regulation of central neurotransmitters (5-HT and BDNF) may alleviate postoperative anxiety and depression and improve cognitive function, thereby interrupting the vicious cycle of psychological stress and abnormal vascular tone." (PMID 41488091, 2025).
depression (continued). "Furthermore, significantly elevated serum levels of BDNF and serotonin (5-HT) in these patients suggested that this natural product could lower depression symptoms." (PMID 40733008, 2025). "Furthermore, a depression model suggests that Nrf2 acts as a transcription factor for BDNF." (PMID 40564462, 2025). "Moreover, studies have indicated that plasma BDNF levels may reflect central BDNF levels, making it a potential biomarker for depression." (PMID 41312464, 2025). "Depression is a heterogeneous condition, meaning that varying biological mechanisms may contribute to its development in different individuals, which could lead to inconsistent BDNF responses across studies." (PMID 40565369, 2025). "However, since schizophrenia exhibits distinct pathophysiological characteristics compared to depression, a mood disorder, further studies using schizophrenia models are needed to better understand the role of BDNF in its pathogenesis and potential therapeutic implications." (PMID 40005159, 2025). "Robust evidence shows a negative correlation between depression scores and peripheral BDNF levels in unmedicated MDD, and more recent meta-analyses have confirmed those findings." (PMID 40943216, 2025). "Thus, our data reinforce the described roles of BDNF deficit in depression and anxiety." (PMID 41237192, 2025). "Similarly, while BDNF is widely reported to be reduced in depression and increased with treatment, recent findings indicate BDNF may rise independently of clinical response, questioning its utility as a dynamic marker of therapeutic progress." (PMID 40428308, 2025). "A lack of BDNF may cause neurological conditions such as Parkinson’s disease, brain atrophy, depression, and Alzheimer’s disease." (PMID 41154631, 2025). "Furthermore, serum BDNF decrease is found in both depression and depression-free psoriasis." (PMID 39959848, 2025). "Their results showed an increase in BDNF levels, accompanied by a general improvement in symptoms, supporting the hypothesis that probiotics have significant therapeutic potential in the treatment of depression." (PMID 38732599, 2024). "Additionally, numerous studies suggest that BDNF may play a potential role in depression by influencing neurogenesis and synaptic plasticity." (PMID 38835076, 2024). "Based on the important role of proBDNF/mBDNF balance in regulating neuronal and synaptic function, it is believed that the decreased BDNF expression in the hippocampus and prefrontal cortex, as well as the resulting changes in synaptic plasticity, are the causes of depression." (PMID 38912176, 2024). "Studies have shown that insufficient BDNF secretion can impede the continued differentiation of immature neurons and greatly reduce synaptic plasticity, neurotransmission, and receptor sensitivity in mature neurons, leading to progressive nerve damage and depression onset." (PMID 39654612, 2024). "Additionally, BDNF expression is reduced, and its functions are altered in those with depression." (PMID 38541632, 2024). "The neuroplasticity hypothesis of depression suggests that a lack of brain-derived neurotrophic factor (BDNF) may cause structural changes in the brain." (PMID 39598400, 2024). "However, research has demonstrated that there is a notably high occurrence of major depression among individuals with type 2 diabetes (T2DM), coinciding with diminished BDNF levels—circumstances that could be linked to the BDNF Val66Met polymorphism." (PMID 38988887, 2024). "Thus, it was determined that there was no statistical association between depression levels and BDNF protein expression in mice." (PMID 39135986, 2024). "The role of physical exercise in increasing BDNF levels is controversial, with some evidence suggesting that acute or chronic exercise programs are able to increase BDNF levels, thus indicating that physical activity can be helpful in treating depression and anxiety, increasing neurogenesis." (PMID 38255692, 2024).